IL21 (interleukin 21)
Diseases named in the same sentence as IL21 in open-access papers (continued):
Sharing a sentence is not in itself a finding about the gene and the disease.
diabetes (continued). "Although it has been demonstrated that IL-21 enhances Th17 differentiation and it can be produced by Th17 cells to exert autocrine feedback, existing data indicated that the role of IL-21 in the development of diabetes is more than just an effect on Th17 differentiation." (PMID 29867762, 2018). "Moreover, IL‐21, the central cytokine produced by Tfh and Tph cells, appears to play a pivotal role in autoimmune diabetes: IL‐21R‐deficient NOD mice are protected from diabetes, whereas IL‐21 overexpression in beta cells precipitates the disease in diabetes‐resistant mice." (PMID 32697399, 2020). "Two cytokine families that are important in diabetes pathogenesis are interferons (IFN), including type 1 IFNs and IFN-γ, and the common γ chain cytokines, including IL-2, IL-4, IL-7, IL-9, IL-15, and IL-21." (PMID 33343569, 2020). "Additionally, the synergistic effect of IL-17A with IL-21 and IFN-γ has been reported to promote diabetes development." (PMID 40979706, 2025). "Conversely, transgenic IL-21 expression in pancreatic islets induced diabetes in non-autoimmune C57BL/6 mice." (PMID 38887289, 2024). "SUMO-defective c-Maf promotes IL-21 expression in T cells, and T cell-specific transgenic NOD mice overexpressing SUMOylation site-defective c-Maf resulted in more rapid development of the diabetes than control mice." (PMID 38280996, 2024). "NOD mice lacking IL-21 or IL-21 receptor were protected from diabetes development, while transgenic expression of IL-21 in pancreatic islets was sufficient to induce diabetes in non-autoimmune prone (C57BL/6) mice." (PMID 35156097, 2021). "Interestingly, the overexpression of IL-21 in pancreatic β cells of C57BL/6 mice resulted in islet destruction and the development of spontaneous T1D in a normally diabetes-resistant C57BL/6 mouse strain." (PMID 33262765, 2020). "The absence of diabetes and insulitis suggests that islet autoimmunity is decreased when IL-21 responses are absent." (PMID 18773086, 2008). "In mice, IL-21 is overproduced in models of autoimmune diabetes, and deficiency in IL-21R was found to prevent the development of diabetes in non-obese diabetic (NOD) mice, while transgenic expression of IL-21 in pancreatic islets was sufficient to trigger diabetes in non-autoimmune C57BL/6 mice." (PMID 38164992, 2024). "In addition, NOD mice fail to develop diabetes in the absence of IL-21, further suggesting that Tfh as well as Th17 are important contributors to β cell autoimmunity." (PMID 33603744, 2020). "Thus we next tested whether type I IFNs or IL-21 were mediators of the observed SOCS1 induction in islet CD8+ T cells and/or were required for CTL differentiation and diabetes development." (PMID 31653894, 2019). "Since T cell effector function was diminished when the IL-21R was absent, we asked whether IL-21 plays a role in precipitating clinical diabetes in NOD mice." (PMID 18773086, 2008). "While anti-IL-21 monotherapy potently prevents diabetes in the NOD model, it does not reverse.It was therefore opted to combine the GLP-1R agonist liraglutide with anti-IL-21, resulting in reversal after hyperglycemia onset in the NOD model." (PMID 30356664, 2018). "Thus, increased expression of IL‐21 and IL‐10 was detected in people with T1D compared with ND (31% and 37% of IL‐10‐producing CD8+ T cells in T1D and T2D participants, respectively, compared with 12% in people without diabetes)." (PMID 41367201, 2025).
COVID-19 (35 papers, 2020 to 2025). A disease caused by infection with severe acute respiratory syndrome coronavirus 2. "In humans, abundant CD4+CD154+ T cells are associated with severe COVID-19, particularly in T cells producing abundant proinflammatory cytokines, including interferon-γ (IFNγ), tumor necrosis factor, interleukin-2 (IL-2) and/or interleukin-21 (IL-21)." (PMID 37856551, 2023). "However, some research suggests that high circulating levels of IL-21 are linked to illness severity in COVID-19 patients." (PMID 35782361, 2022). "In our dataset, TFH cells showed increased expression of IL21 in convalescent COVID-19 compared with acute disease and control samples, with little IL4 detectable." (PMID 39890933, 2025). "And, spike-specific CXCR3+ TFH cells exhibited higher activation status and greater IL-21 secretion than spike-specific CXCR3− TFH cells in both COVID-19 convalescents and vaccinees upon antigen exposure." (PMID 37802996, 2023). "It has also been reported that NK cell-activating cytokines such as IL-12, IL-15 and IL-21 are reduced in individuals with COVID-19." (PMID 36936055, 2023). "As a result, a clinical trial exploring the combination of IL-15 and IL-21 for COVID-19 patients is recommended." (PMID 35782361, 2022). "Seven-day cultures of IL-21/CD40L-stimulated MBCs isolated from the blood of Sputnik V vaccinees secreted anti-RBD IgG at approximately the same level as MBCs from acute COVID-19 patients." (PMID 35280987, 2022). "In COVID-19 patients, measurement of serum IL-21 shows a high predictive value for disease development." (PMID 35782361, 2022). "Plasma levels of IL-6, TNFα, IL-1β, IL-10 and IL-21 were significantly higher in Asymptomatic COVID-19 cases as compared with Controls." (PMID 34824360, 2021). "Studies have shown increased levels of IL-21 and IL-22 in plasma of patients hospitalised with COVID-19." (PMID 34205262, 2021). "A treatment method aimed at activating NK cells and CD8+ T cells using IL-15 for COVID-19 has been proposed, and Wilz argued that IL-21 should be added to this treatment." (PMID 34502427, 2021). "The CD4+ TH1-lineage was similarly characterized by increased IFN- (type I and II) and interleukin (IL6, IL12, IL21) signaling in mild COVID-19." (PMID 33473155, 2021). "While we did not observe any significant difference in the levels of IFNα and IFNγ in our study group, higher IL-21 levels in severe COVID-19 patients suggests the existence of a hyper inflammatory condition in this group." (PMID 34199203, 2021). "The obvious involvement of IL-21 in the instruction of plasmablasts of COVID-19 patients points to cognate B cell activation by follicular helper T (Tfh)/Th17 cells, which are the main producers of IL-2135." (PMID 33785765, 2021). "IL-21 is produced by follicular helper CD4+ T-cells that sustain B-cell functions, while IL-33 levels are associated with exacerbated pulmonary inflammation in COVID-19." (PMID 40573439, 2025). "Nonetheless, the finding that on average 72% of patients exhibited a SARS-CoV-2-specific IL-21 memory T-cell response 6 mo after the last vaccination with no COVID-19 in the meantime, underlines the durability of this response." (PMID 38902860, 2024). "The higher median IgM, IgA, and IgG1 values in the sera of the MIS-C cohort to some of the COVID-19 Ags may relate to the higher type-2 cytokines (IL-4, IL-5, IL-6, and IL-13) and IL-21 enhanced Tfh activity known to promote B-cell activities." (PMID 38932242, 2024). "The study also determined that Treg cell responses during COVID-19 may lead to more severe outcomes in humans, which is seemingly contradictory considering IFNγ- and IL-21-expressing T cells appeared to contribute to immunopathology." (PMID 37856551, 2023). "Furthermore, PBMCs isolated from severe COVID-19 patients at the acute phase of disease produced higher levels of IL-21, IFNγ, IL-4, and IL-17 in response to spike and RBD, than PBMCs from mild patients." (PMID 37061513, 2023).
COVID-19 (continued). "Th17 cells during COVID-19 are characterized by phenotype typical to tissue resident memory T cells also expressing the genes associated with cytolytic potential (SRGN, GZMB, and GNLY) and cytokine genes encoding IL-21, IL-17F, IL-17A, IFN-γ, and GM-CSF." (PMID 37626620, 2023). "Again, IL-21 supernatant concentrations were higher in co-cultures with cells isolated from severe COVID-19 patients compared to mild patients or healthy controls, suggesting that the functionality of overall cTfh cells is more potent in severe compared to mild COVID-19." (PMID 37061513, 2023). "First, we studied the profile of different soluble pro-inflammatory cytokines (GM-CSF, TNF-α, IFN-γ, IL-1β, IL-2, IL-6, IL-7, IL-10, IL-17A, IL-21) and chemokines mediating monocyte and neutrophil recruitment (IL8, CCL3), whose exacerbated production is associated with severe COVID-19." (PMID 36675231, 2023). "One possible reason for this might be that cTfh cells isolated from severe COVID-19 patients produce higher amounts of IL-21, a critical cytokine for B-cell differentiation and antibody production, compared to cTfh cells isolated from mild patients." (PMID 37061513, 2023). "In addition, in the case of people with a severe course of COVID-19, a greater Th17 response and related interleukin-17 (IL-17), interleukin-21 (IL-21), interleukin-22 (IL-22) and granulocyte-macrophage colony-stimulating factor (GM-CSF) were also noted." (PMID 36294388, 2022). "IL-4 production is observed in trials as mentioned following COVID-19 vaccination, whereas data about IL-17 and IL-21 which are viewed as the protective factor of vaccine-induced immunity, are still missing in patients developing pemphigus following COVID-19 vaccine administration." (PMID 35887732, 2022). "In severe COVID-19, IL-21 and TGF-β may be imbalanced, and the pathological condition is exacerbated." (PMID 34502427, 2021). "Additionally, TFH cells predominantly produce IL-2, IL-4 and IL-21 in B cell follicles and closely regulate antibody class-switching in severe inflammatory and allergic diseases, including AD, asthma, and COVID-19-induced airway inflammation." (PMID 34531749, 2021). "In addition, it has been reported that spike protein-specific memory B cell differentiation and antibody affinity maturation in mildly recovered COVID-19 and severely ill patients correlate well with the function of IL-21-producing CD4+ T cells." (PMID 34502427, 2021). "In acute COVID-19, IL-21 and TGF-β may be out of balance, thus exacerbating the pathological state." (PMID 35782361, 2022). "A previous study showed that the plasma cytokine levels such as IL-6, IL-1β, IL-10, IL-21, and TNF-α were significantly higher in asymptomatic group compared to the controls, indicating an increased inflammation in asymptomatic COVID-19 patients." (PMID 37869674, 2023). "In contrast, the highest contributors to dimension 1 were IL-21, IL-2, IL-1b, IL-17A, GM-CSF, IFN-γ, IL-7 and CCL3, and these cytokines were significantly decreased in acute COVID-19 patients in comparison to HC." (PMID 34572439, 2021). "The present data indicate that DPSC administration might be effective in patients with COVID-19-induced hyper-inflammation, due to the inhibition in the production of several cytokines by activated T lymphocytes, namely, IFNγ, TNFα, IL-2, IL-9, IL-10, IL-17A, IL-18, IL-21, and IL-27." (PMID 33634100, 2020). "Intriguingly, the amount of IL-21 secreted by CXCR3+ TFH cells was significantly higher than that secreted by CXCR3− TFH cells from both COVID-19 convalescents and vaccinees, but not from healthy controls, upon peptide stimulation." (PMID 37802996, 2023). "However, HD patients with COVID-19 symptom worsening showed up-regulation (more than 2.5-fold increase) of GM-CSF, IFN-γ, IL-1β, IL-2, IL-6, IL-17A and IL-21, and down-regulation of TNF-α and IL-8 serum levels after the dialysis procedure." (PMID 36675231, 2023).
COVID-19 (continued). "In aggregated analysis, Eotaxin-3 and Eotaxin-1 levels decreased in COVID-19 patients; however, in sex-segregated analysis, Eotaxin-3, CCL5, IL-21, and IL6+CD4+ T cell levels were lower in female versus male HCW and this sex difference was maintained in female versus male COVID-19 patients." (PMID 37998327, 2023). "Interestingly, higher concentrations of IL-21 and IFN-γ have been also demonstrated in COVID-19 convalescent plasma." (PMID 34205262, 2021). "Intracellular IL-21 secretion was significantly increased in TFH cells, CXCR3+ TFH cells, and CXCR3− TFH cells from both COVID-19 convalescents and vaccinees, but not from healthy controls, upon peptide stimulation." (PMID 37802996, 2023). "Interestingly, pro-inflammatory cytokines—such as IFN-gamma, TNF, IL-23, IL-15, IL-21 and IP-10/CXCL-10—were detected both in the sera of severe ICU hospitalized and of non-hospitalized COVID-19 patients." (PMID 33019628, 2020).
asthma (34 papers, 2008 to 2026). "Studies have shown that Th17-associated cytokines, including IL-17A and IL-21, are upregulated in neutrophilic and corticosteroid-resistant asthma." (PMID 41601686, 2026). "Overall, the results provide new insight into the potential design of Breg-based or IL-21-based therapeutic strategies for allergic diseases, including asthma associated with DOCK8 deficiency." (PMID 34867940, 2021). "Data from this study provide new insight into the potential design of Breg-based or IL-21-based therapeutic strategies for allergic diseases, including asthma in those with DOCK8 deficiency." (PMID 34867940, 2021). "Several cells and mediators have been linked to T2-low asthma, including the activation of Th1 and Th17, neutrophil infiltration, and cytokines IL-8, IL-17, IL-21, and IL-22." (PMID 33513844, 2021). "As evidenced in recent clinical studies, the frequency of cTFH cells and/or the IL-21 level in peripheral blood mononuclear cells (PBMCs) appear to be the promising diagnostic biomarkers for IgE production and asthma symptoms." (PMID 31921177, 2019). "Arginase-1 in macrophages is induced by Th2 type cytokines such as IL-4, IL-10, IL-13 and IL-21 and increased arginase is associated with resistance to worm infections, allergic conditions such as asthma and Th2 induced pathologies." (PMID 19696894, 2009). "Clinical studies have shown that the frequency of TFH cells in peripheral blood mononuclear cells and/or IL-21 levels is positively correlated with IgE levels, which may be promising diagnostic biomarkers for asthma." (PMID 36393974, 2022). "Additionally, an increased IL-21 level appears to be associated with increased infiltration of inflammatory cells in the submucosa and is correlated with asthma severity." (PMID 31921177, 2019). "cTFH cells and IL-21 levels can be potentially included in future diagnostic criteria for asthma." (PMID 31921177, 2019). "In severe asthma, where neutrophils are dominant, T-helper 17 (Th 17) cells secrete IL-17 A, IL-17 F, IL-21, IL-22, and TNF-α which drive inflammation and airway hyperresponsiveness." (PMID 40605076, 2025). "In the early stage of asthma, the concentrations of IL-6 and IL-21 are likely insufficient to induce Th17 differentiation." (PMID 38629073, 2024). "The indirect effects of MICB, PDE4D, and IL‐21 on childhood asthma via BMI were relatively modest, at 3.31%, 5.03%, and 3.43%, respectively." (PMID 38730525, 2024). "Other cytokines, IL-21 activate Th17 in an autocrine manner, while TNF-α is associated with airway inflammation in severe asthma." (PMID 37377958, 2023). "These cells produce IL-21 and IL-4, which are essential for B-cell stimulation and play a key role in controlling IgE production in asthma." (PMID 37377958, 2023). "TFH cells and iconic cytokine IL-21 are related to asthma progression and affect the production of IgE in asthma." (PMID 36393974, 2022). "The levels of IL-4 and IL-17 in the recurrent infection group were significantly higher than those in the asthma group, while the levels of IL-21 were significantly lower than those in the asthma group." (PMID 35991273, 2022). "The vitro model of asthma treated with miRNA-221-5p mimic resulted in the reduction of IL-6, IL-17, IL-21 and IL-22 levels, and induction of IL-10, IL-35 and TGF-β levels." (PMID 34863307, 2021). "We found that recombinant murine (rm)IL-21 restored the function of Bregs both in vitro and in Dock8 KO mice, leading to reduced inflammatory cell infiltration of the lungs in a murine asthma model." (PMID 34867940, 2021). "We also found that IL-21 rescued the function of Bregs in Dock8 KO mice and alleviated inflammatory infiltration in a murine asthma model." (PMID 34867940, 2021). "In this study, we examined the levels of IL-4, IL-5, and IL-21, which are involved in the pathology of asthma." (PMID 32143340, 2020).